PHLDB2 (pleckstrin homology like domain family B member 2)
Diseases named in the same sentence as PHLDB2 in open-access papers (continued):
Sharing a sentence is not in itself a finding about the gene and the disease.
tumor (9 papers, 2016 to 2025). "Various studies have indicated that high levels of PHLDB2 expression are linked to a poor prognosis in multiple tumor types." (PMID 38397469, 2024). "We also observed that PHLDB2 expression was lower in RCC tumor tissues and associated with the OS rate through a Kaplan‐Meier analysis of the TCGA data." (PMID 33320958, 2021). "In the present report, by following our previous study, we found that PHLDB2 expression is associated with poorer prognosis, including disease-free survival, tumor stage, nodes pathology, as well as lymphatic and vascular invasion through TCGA data analysis." (PMID 31346319, 2019). "In the attempt to find association between PHLDB2 and tumor invasiveness, we found that patients with either lymphovascular invasion or vascular invasion also have significantly higher expression of PHLDB2 than those without these indicators." (PMID 31346319, 2019). "Analysis of tumor growth curves revealed that the Phldb2‐knockdown group exhibited significantly slower tumor progression." (PMID 41319208, 2025). "These transcriptional changes were corroborated by corresponding protein‐level modifications in western blot analyses, suggesting PHLDB2's regulatory role in tumor cell proliferation and migration through EMT modulation." (PMID 41319208, 2025). "To further investigate the role of PHLDB2 in tumor progression in vivo, we established a stable Phldb2‐knockdown 4t1 cell line (4t1‐shPhldb2) using the murine TNBC cell line 4t1." (PMID 41319208, 2025). "This trend was also evident in TNBC, where PHLDB2 exhibited notably lower expression in tumor tissues compared to normal tissues (p < 2e−16)." (PMID 41319208, 2025). "In vivo, Phldb2 depletion markedly reduced tumor growth and pulmonary metastases and prolonged survival in TNBC‐bearing mice." (PMID 41319208, 2025). "The results demonstrated significant reductions in tumor volume and weight in the PHLDB2-knockdown cells compared to those in control mice." (PMID 38397469, 2024). "The results showed that tumors with PHLDB2 knockdown significantly impede the growth of HNSCC by inducing CD8+ T cell-mediated anti-tumor immunity." (PMID 38397469, 2024). "Mechanistically, PHLDB2 was found to be involved in the regulation of T cell anti-tumor immunity, primarily by enhancing the activation and infiltration of CD8+ T cells." (PMID 38397469, 2024). "A significant finding of this study was that PHLDB2 modified tumor-infiltrated T cells to optimize antitumor immune responses in HNSCC." (PMID 38397469, 2024). "PHLDB2 has also been reported as a direct target of miR-29c-3p, a tumor-suppressive miRNA inhibiting migration and invasion of CRC cells." (PMID 33452458, 2021). "In our own tissue samples from Sir Run Run Shaw Hospital, we also observed downregulation of PHLDB2 in tumor tissues compared to normal tissues (**P < .01)." (PMID 33320958, 2021). "The results indicated that PHLDB2 was downregulated in tumor tissues compared to adjacent tissues and the expression level of PHLDB2 was negatively associated with the OS rate (P < .001)." (PMID 33320958, 2021). "In analysis of the TCGA data in the Wanderer, the methylation levels of PHLDB2 promoter regions were significantly different between tumor and normal tissues." (PMID 33320958, 2021). "In support of our previous findings, we observed worse outcomes in several clinical categories, including disease-free survival, AJCC tumor stages and nodes pathology, and lymphovascular and vascular invasion, in patients with higher PHLDB2 expression." (PMID 31346319, 2019). "The pleckstrin homology‐like domain family B member 2 (PHLDB2) has been implicated in cytoskeletal organization and cell migration, but its role in phase separation–mediated tumor progression has not been explored." (PMID 41319208, 2025). "This suggests that PHLDB2 may function through liquid–liquid phase separation mechanisms, contributing to its role in tumor progression and cellular organization." (PMID 41319208, 2025).
tumor (continued). "In conclusion, our data support the notion that the PHLDB2 gene may significantly impact tumor immunity." (PMID 38397469, 2024). "Furthermore, we found that the depletion of PHLDB2 significantly delayed tumor growth and enhanced the infiltration and function of CD8+T cells in a mouse model of HNSCC bearing a C3H tumor." (PMID 38397469, 2024). "Furthermore, we demonstrated that the ablation of PHLDB2 in tumor cells inhibited tumorigenicity in a C3H syngeneic tumor-bearing mouse model." (PMID 38397469, 2024). "In addition, the study found that IGF2BP2 and its co-expressed genes (HMGA2, PHLDB2, and YEATS2) are all associated with a variety of TICs in OSCC tumor samples." (PMID 35129592, 2022). "However, in vivo experiments showed that PHLDB2 markedly inhibited tumor growth." (PMID 38397469, 2024). "The PHLDB2‐CLASP interaction facilitates focal adhesion disassembly and promotes cell migration, serving as an independent prognostic marker for poor tumor outcomes." (PMID 41319208, 2025). "Consequently, blocking PHLDB2 could be a promising strategy for anti-tumor purposes." (PMID 38397469, 2024). "For a more comprehensive evaluation of PHLDB2 expression in HNSCC, immunostaining was performed on tumor tissues and adjacent normal tissues." (PMID 38397469, 2024). "Therefore, it is crucial to investigate the potential role of PHLDB2 in the EMT and anti-tumor immunity in HNSCC." (PMID 38397469, 2024). "In this study, we show that PHLDB2 depletion induces effective antitumoral immunity through recruitment of cytotoxic CD8+ T cells and the remodeling of the tumor microenvironment in HNSCC, which suggests that targeting PHLDB2 may be an effective strategy to improve PD-1 immunotherapy." (PMID 38397469, 2024). "Thus, targeting PHLDB2 may enhance the anti-tumor function of T cells and potentially exert anti-tumor immunity in HNSCC cells rather than directly suppressing tumor cell proliferation." (PMID 38397469, 2024).
PHLDB2 also shares sentences with these, for which no sentence is quoted: lung adenocarcinoma (3 papers); adenoma (1); bladder cancer (1); colorectal tumor (1); diffuse large B-cell lymphoma (1); invasive breast carcinoma (1); lung fibrosis (1); lung squamous cell carcinoma (1); lymphoid neoplasm (1); ovarian carcinoma (1); pancreatic adenocarcinoma (1); pancreatic cancer (1); preeclampsia (1).